PCDH19 (protocadherin 19)
Diseases named in the same sentence as PCDH19 in open-access papers (continued):
Sharing a sentence is not in itself a finding about the gene and the disease.
epilepsy (continued). "Moreover, our new findings of the male mosaic variant broaden the spectrum of PCDH19-related epilepsy and provide a new understanding of this complex genetic disorder." (PMID 29866057, 2018). "Although PCDH19-related epilepsy is an X-linked dominant disorder almost exclusively affecting females, five males were found to be mosaic for a pathogenic variant in the PCDH19 gene and presented with epilepsy and/or developmental delay, similar to females with PCDH19 pathogenic variants." (PMID 28837158, 2018). "The strong association of PCDH19 with epilepsy inheritance is also stressed by genetic screening demonstrating that 11 out of 45 patients suffering from Dravet syndrome (severe myoclonic epilepsy of infancy) carried mutations in PCDH19." (PMID 30298130, 2018). "Thus, the protocadherin-19 (Pcdh19), a potential target of miR-3065-5p, is regulated in the hippocampus in response to a plasticity paradigm, and mutations on Pcdh19 are responsible for epilepsy and mental retardation." (PMID 30456375, 2018). "It is now clear that PCDH19 pathogenic variants can cause epilepsy both in males and females and that mosaicism for PCDH19 pathogenic variants in males might be more common than previously thought." (PMID 28669061, 2017). "Epilepsy caused by PCDH19 gene mutation in humans has an infantile onset, suggesting the possibility that PCDH19 might be involved in brain development." (PMID 28724954, 2017). "Moreover, mutations in the X-chromosomal protocadherin gene PCDH19 cause epilepsy and intellectual disability in females." (PMID 25950944, 2015). "However, a PCDH19 mutation was found to be responsible for epilepsy and mental retardation confined to females (EFMR)." (PMID 22453032, 2012). "In conclusion, these results extend the mutational and clinical spectra associated with PCDH1 9-related epilepsies and show that mutations in PCDH19 are a frequent cause of epilepsy in females and should be considered even in absence of family history and/or mental retardation." (PMID 21053371, 2011). "Refractory epilepsy, caused by PCDH19 pathogenic variants, is a highly drug-resistant condition, but molecular diagnosis has allowed us to apply Ganaxolone in our patients, a drug whose effectiveness in females with PCDH19 variants has been recently confirmed in clinical trials." (PMID 36674629, 2023). "Besides, PCDH19 variants in two loci were identified in our research, and the p.Asn232Ser has been reported in previous cases of the clinical diagnosis of PCDH19-related epilepsy or Dravet syndrome with phenotype heterogeneity." (PMID 36970538, 2023). "Therefore, whether the variant is located upstream of EC5 or not may be crucial for determination of phenotypic severity with regard to seizure onset age and intellectual disability in patients with PCDH19-related epilepsy carrying truncating variants." (PMID 33262389, 2021). "Altogether, these results indicate that PCDH19 downregulation enhances neuronal intrinsic excitability and suggest a causal link between reduced GABAergic transmission and hyperexcitability, with important implications for the pathogenesis of PCDH19-related epilepsy." (PMID 32880860, 2020). "In the present study, we assessed mutations in the PCDH19 gene and the clinical features of a group of Chinese patients with early infantile epileptic encephalopathy and aimed to provide further insight into the understanding of epilepsy and mental retardation limited to females (EFMR; MIM 300088)." (PMID 29866057, 2018). "However, the patient with the H203P mutation also carries another PCDH19-FE mutation (F206C) at a location mutated in other epilepsy patients; thus it is unclear if H203P is contributing to epilepsy." (PMID 27787195, 2016). "As an in vitro epilepsy model, this system effectively recapitulates key neurophysiological features of PCDH19-CE, including neuronal hyperexcitability and network dysfunction." (PMID 41301876, 2025).
epilepsy (continued). "The case is extremely important for expanding the latest symptoms of PCDH19-related epilepsy and providing potential reference value for clinical diagnosis." (PMID 39792735, 2025). "Moreover, cellular mosaicism in females may lead to cellular interference, where interactions between wild-type-expressing and mutant-expressing cells generate emergent tissue-level effects, a phenomenon also proposed in other X-linked epilepsies such as the PCDH19 clustering epilepsy." (PMID 41153413, 2025). "An interesting phenomenon is that it presented the phenotype of frequent abdominal pain as a seizure type of PCDH19-related epilepsy." (PMID 39792735, 2025). "In PCDH19-related epilepsy, which primarily affects females, clustered seizures frequently progress to refractory status epilepticus (SE), wherein conventional treatments fail." (PMID 40290041, 2025). "We report the case of a young girl with PCDH19-related epilepsy who presented with frequent abdominal pain identified as a novel seizure type of PCDH19 gene variants." (PMID 39792735, 2025). "Although multiple seizures are frequently reported with PCDH19-related epilepsy, initial presentation as frequent abdominal pain in children has not been well reported." (PMID 39792735, 2025). "The KD significantly reduces SE episodes and thus offers a critical alternative therapy for the management of PCDH19-related epilepsy." (PMID 40290041, 2025). "Our report expanded the phenology spectrum of PCDH19-related epilepsy and provided potential reference value for the clinical diagnosis." (PMID 39792735, 2025). "Among patients with PCDH19-related epilepsy, heterozygous females and a few mosaic males are affected predominantly; nonmosaic hemizygous males are asymptomatic unlike in a typical X-linked condition." (PMID 38891919, 2024). "PCDH19 epilepsy has an estimated incidence of about 1 per 21,000 live births and is caused by mutations in the PCDH19 gene, which encodes a protocadherin belonging to the cadherin superfamily of cell-adhesion proteins." (PMID 38424476, 2024). "In PCDH19-related epilepsy, genetic counselling and clinical geneticists play an essential role in the recognition of the disease, the selection of the appropriate diagnostic test, and the identification of affected family members." (PMID 38891919, 2024). "The overall estimated annual incidence of single-gene epilepsies in this population was 1 per 2120 live births (47.2/100 000; 95% CI 36.9 to 57.5), with pathogenic variants in SCN1A, PCDH19, CDKL5 and KCNQ2, having the highest incidence for DEE." (PMID 39613335, 2024). "We discovered the combinatorial expression of Protocadherin-19(Pcdh19), a protein involved inPCDH19-clustering epilepsy, with Pcdh1, Pcdh9 or Cadherin 13 (Cdh13) in excitatory neurons." (PMID 38629124, 2024). "PCDH19-related epilepsies are among the eight most common single-gene epilepsies, with an incidence of 1 per 20,600 live-born females, and a prevalence of 4.85/100,000 (95% CI 1.97–9.15)." (PMID 38238304, 2024). "Several mechanisms have been proposed to contribute to the pathophysiology of PCDH19 epilepsy including GABA receptor dysregulation, blood-brain barrier dysfunction, impaired steroid metabolism, asynchronous neurogenesis, and cellular interference." (PMID 38424476, 2024). "Our results support the opportunity for reduced penetrance in DEE9 and contribute to expanding the genotype–phenotype spectrum of PCDH19-related epilepsy." (PMID 38891919, 2024). "Altogether, these data indicate that Pcdh19 mosaic mice are characterized by an aberrant configuration of their network states, a phenomenon typically observed in epilepsy and its comorbidities." (PMID 36997609, 2024).
epilepsy (continued). "This neurosteroid, being a positive allosteric modulator of GABAA receptors, is also used in the treatment of epilepsy related to PCDH19 clusters, status epilepticus accompanying Dravet syndrome, and infant convulsions following hypoxic brain damage." (PMID 38003469, 2023). "For example, variants in the gene encoding protocadherin-19 (PCDH19) are the cause of developmental and epileptic encephalopathy, type 9, also known as epilepsy, and mental retardation restricted to females (EFMR)." (PMID 36674629, 2023). "These variants result in intractable early-onset epilepsy (with some features similar to PCDH19 clustering epilepsy), progressive neurodevelopmental impairment, and (in some) regression." (PMID 37107610, 2023). "Due to random X-chromosome inactivation, protocadherin 19 clustering epilepsy-affected females present a mosaic population of healthy and protocadherin 19-mutant cells." (PMID 35528232, 2022). "Protocadherin 19 gene-related epilepsy or protocadherin 19 clustering epilepsy is an infantile-onset epilepsy syndrome characterized by psychiatric (including autism-related), sensory, and cognitive impairment of varying degrees." (PMID 35528232, 2022). "Unfortunately, to date, no current mouse model can fully recapitulate both the brain histological and behavioural deficits present in people with protocadherin 19 clustering epilepsy." (PMID 35528232, 2022). "Protocadherin 19 female epilepsy (PCDH19-FE) is an increasingly reported form of epilepsy whose pathophysiology is poorly understood." (PMID 35250833, 2022). "Here we presented an extensive physiological characterization of cortical activity in a mouse model of PCDH19 epilepsy." (PMID 35741068, 2022). "Ganaxalone has been trialed for epilepsies including epileptic spasms, status epilepticus and protocadherin 19 related epilepsy." (PMID 35795799, 2022). "Mutations in the protocadherin 19 (PCDH19) gene located on chromosome X (Xp22.1) cause female-limited epilepsy [PCDH19 gene-related epilepsy or PCDH19 clustering epilepsy (PCDH19-CE); OMIM #300088]." (PMID 35528232, 2022). "Pcdh19 is becoming one of the most clinically relevant genes in epilepsy, yet little is known about its function." (PMID 35741068, 2022). "The known involvement of hormonal pathways in the pathogenesis of PCDH19-related epilepsy has prompted researchers to look for steroid-based treatments for this disorder." (PMID 35250833, 2022). "It has been studied for the management of some refractory epilepsies, including PCDH19-related epilepsy." (PMID 36004035, 2022). "This literature review will give a better understanding of this disorder and the pathophysiological basis of PCDH19-related epilepsy." (PMID 35822151, 2022). "Protocadherin-19 (PCDH19) is a synaptic cell-adhesion molecule encoded by X-linked PCDH19, a gene linked with epilepsy." (PMID 35613587, 2022). "PCDH19 clustering epilepsy (PCDH19-CE; MIM 300088) is a rare form of drug-resistant epilepsy caused by mutations or partial deletions of the PCDH19 gene." (PMID 35408865, 2022). "The clinical characteristics of PCDH19-related epilepsy are represented by early onset (6–36 months) seizures, generally sensitive to fever." (PMID 35978409, 2022). "Based on these recent findings, the name of this disorder has recently been changed from “female restricted epilepsy with intellectual disability” to PCDH19 clustering epilepsy (PCDH19-CE)." (PMID 34201522, 2021). "PCDH19-related epilepsy is characterized by an unusual pattern of inheritance, as affected patients are generally females heterozygous for a pathogenic PCDH19 variant." (PMID 34201522, 2021). "Although epilepsy and mental retardation limited to female (EFMR) is the most frequent clinical expression of PCDH19 mutation, other important clinical manifestations are genetic epilepsy with febrile seizure plus (GEFS+) and epileptic encephalopathies." (PMID 35111125, 2021).
epilepsy (continued). "We reviewed the papers (English language only) on PCDH19-related epilepsy through a Literature search on PubMed until August 2021." (PMID 35111125, 2021). "Next, we assessed the phenotypic differences of patients with PCDH19-related epilepsy, including the age of seizure onset, seizure type, behavioral features, and intellectual disability level, according to variant type using clinical data." (PMID 33262389, 2021). "Most mosaic males (88.9%: 24/27) showed seizure-related features, whereas, 83.3% (10/12) of hemizygous males were unaffected, in accordance with previously suggested pathomechanisms of PCDH19-related epilepsy." (PMID 33262389, 2021). "The broad phenotypic spectrum of PCDH19-related epilepsy has been extensively studied in recent years and has led to improved and earlier recognition of symptoms." (PMID 35111125, 2021). "In this study, we updated pathogenic variants by collecting data from published and unpublished reports of patients with PCDH19-related epilepsy." (PMID 33262389, 2021). "Mutation in PCDH19 cause epileptic encephalopathy, early infantile, 9 (EIEE9, OMIM:300088), also known as epilepsy and mental retardation restricted to females (EFMR)." (PMID 33287870, 2020). "The protocadherin genes, PCDH10 and PCDH19 that are linked to ASD and epilepsy were downregulated along with several members of Zinc-finger gene family of transcription factors." (PMID 31921404, 2020). "PCDH19-related epilepsy also known as epilepsy and mental retardation restricted to females (EFMR) is characterized by a distinctive pattern of X-linked inheritance, where heterozygous females exhibit seizures and hemizygous males are asymptomatic." (PMID 33287870, 2020). "In particular, genes such as ANXA1, CNTN6, HLA-B, PCDH19, and PCDH10, have been linked to ASD, epilepsy, ID, and other neuropsychiatric disorders, were significantly upregulated or downregulated and warrant further investigation." (PMID 31921404, 2020). "Subsequent studies highlighted that most patients had focal epilepsy clusters triggered by fever, so “PCDH19 girls clustering epilepsy” (PCDH19‐GCE) was proposed as a name to facilitate clinical identification of this disorder." (PMID 31714027, 2019). "Our data show that PCDH19 regulates fine-scale cortical neuronal connectivity, which would contribute to abnormal brain activity and epilepsy in disease conditions." (PMID 31477701, 2019). "PCDH19‐related epilepsy is characterized by incomplete penetration rate and phenotypic heterogeneity." (PMID 31714027, 2019). "Now, PCDH19 has become the second most relevant gene in epilepsy after SCN1A (Depienne & LeGuern, 2012; Duszyc, Terczynska, & Hoffman‐Zacharska, 2015)." (PMID 31714027, 2019). "We therefore proposed “girls clustering epilepsy” (PCDH19-GCE) as a name to facilitate clinical identification of this disorder." (PMID 29892053, 2019). "Epilepsy in Females with Mental Retardation (EFMR) is reportedly caused by mutations (i.e., missense, nonsense, and deletion, etc.)in the X-linked gene protocadherin 19 (PCDH19)." (PMID 31747920, 2019). "The link between the protocadherin-19 (PCDH19) gene and epilepsy suggests that an unusual form of X-linked inheritance affects females but is transmitted through asymptomatic males." (PMID 29866057, 2018). "The importance of examining intrafamily δ-Pcdh interactions was recently underscored by a study examining the role of δ-Pcdh adhesion in PCDH19-GCE (girls clustering epilepsy), a form of epilepsy limited to females." (PMID 30547884, 2018). "Most typically PCDH19-related epilepsy is characterized by early-onset of seizures (6–36 months) followed by recurrent seizures appearing throughout childhood." (PMID 30298130, 2018). "The results from our current study provide new insight into and perspectives for the molecular genetic link between epilepsy and PCDH19 alterations." (PMID 29866057, 2018).
epilepsy (continued). "Due to its female-limited expression PCDH19 gene escaped epilepsy mapping until systematic sequencing of X-chromosome exons clearly revealed mutations of the PCDH19 gene as the cause of the disorder." (PMID 30298130, 2018). "We described three variations in the PCDH19 gene in Chinese patients with epilepsy who developed generalized seizures occurring in clusters with or without triggering by fever." (PMID 29866057, 2018). "Mutations in protocadherin-19 (PCDH19) result in a female-limited, infant-onset form of epilepsy (PCDH19-FE)." (PMID 27787195, 2016). "We focused on the female iPSC model to characterize the PCDH19 biological function in order to transfer the acquired information on the PCDH19 related epilepsy model that needs to be developed in the future." (PMID 26450854, 2015). "These deletions constitute the first micro-rearrangements involving PCDH19 identified in female patients with febrile seizures and epilepsy." (PMID 21053371, 2011). "Mutations in PCDH19 were recently reported to cause EFMR, which also associates mental retardation and epilepsy exclusively in females." (PMID 19214208, 2009). "Mosaic mutations in the X-linked cell adhesion molecule Protocadherin 19 (PCDH19) lead to epilepsy with cognitive impairment, whereas complete absence of functional protein, although possibly linked to autistic features, does not elicit any seizures." (PMID 42303573, 2026). "This phenomenon is exemplified by hemizygous males with PCDH19 mutations, who typically do not exhibit symptoms associated with PCDH19-related epilepsy." (PMID 40870033, 2025). "our report described a girl with abdominal pain as a novel manifestation of PCDH19-related epilepsy and might expand its phenotypes spectrum." (PMID 39792735, 2025). "This may cause symptoms in individuals with heterozygous variants due to an imbalance in PCDH expression, potentially leading to similar disrupted adhesion affinities to those seen in PCDH19-related epilepsy." (PMID 40870033, 2025). "Lastly, the exclusion of gene mutations associated with fever-sensitive epilepsies, such as the SCN1A gene coding for the DNA polymerase subunit gamma-1 (POLG-1) and the protocadherin 19 (PCDH19) gene, may aid the diagnosis of FIRES." (PMID 41462849, 2025). "In a phase 2 clinical study aimed to assess the efficacy of ganaxolone in Protocadherin 19 (PCDH19) clustering epilepsy enrolled 21 females aged 1-17 years with molecularly confirmed PCDH19 variants, experiencing at least 12 seizures during the 12-week screening period." (PMID 39219949, 2024). "PCDH19 (NM_001184880.2) is one of the most clinically relevant genes in epilepsy." (PMID 38891919, 2024). "In contrast to epilepsy, which was shown to require the interaction between two neuronal populations, one of which carries the PCDH19 mutation, the pathogenesis of autism does not seem to be related to cellular interference." (PMID 36980870, 2023). "In addition to the comprehensive analysis of the pedigree with epilepsy and developmental delay from the clinical perspective, the sequencing of epilepsy-related genes was performed to investigate PCDH19 genotype and phenotype heterogeneity." (PMID 36970538, 2023). "Heterozygous PCDH19 variants have been linked to epilepsy in females with mental retardation (EFMR), while mosaic PCDH19 mutations in males are responsible for treatment-resistant epilepsy presenting similarly to EFMR, with some reported cases of comorbid intellectual disability and autism." (PMID 36980870, 2023).